SNORD55 (small nucleolar RNA, C/D box 55)
Synonyms: U55; U39; RNU39; RNU55; SNORD39
Gene: Small nucleolar RNA gene on chromosome 1 (44,775,864 to 44,775,943, forward strand). Ensembl gene ENSG00000264294.
Gene Ontology:
Biological process: RNA processing
Cellular component: nucleolus
Homologues: Orthologues: chimpanzee SNORD39 (100% identical), macaque SNORD39 (99% identical), guinea pig SNORD55 (92% identical), dog SNORD39 (90% identical), mouse Snord55 (89% identical), rat Snord55 (88% identical), pig SNORD39 (85% identical), rabbit SNORD55 (84% identical), pig SNORD39 (71% identical), tropical clawed frog SNORD39 (60% identical), tropical clawed frog SNORD39 (59% identical). Paralogues in human: SNORD39 (72% identical), SNORD39 (71% identical), SNORD39 (69% identical), SNORD39 (68% identical).
Diseases named in the same sentence as SNORD55 in open-access papers:
SNORD55 is named in the same sentence as 3 diseases in open-access papers, as found by Europe PMC text mining. Sharing a sentence is not in itself a finding about the gene and the disease.
SNORD55 shares sentences with these, for which no sentence is quoted: deafness (1 paper); diabetes (1); leukemia (1).